ERG (ETS transcription factor ERG)
Diseases named in the same sentence as ERG in open-access papers (continued):
Sharing a sentence is not in itself a finding about the gene and the disease.
prostate carcinoma (continued). "While therapeutic targeting of transcription factor oncogenes is intrinsically challenging, on the basis of the interaction of ERG with the DNA repair enzyme PARP1 and DNA protein kinase DNA-PKc, use of PARP inhibitors was shown to inhibit growth of TMPRSS2-ERG-positive prostate cancer xenografts." (PMID 26684754, 2015). "The 9FY monoclonal antibody was found to be highly specific in the detection of ERG protein in cell culture-based experiments and human prostate cancer specimens by immunofluorescence and immunohistochemistry (IHC), respectively, without cross-reactivity to other members of the ETS family." (PMID 25889691, 2015). "As cancer develops from glands which are the same as prostate cancer, ERG may also be related with lung adenocarcinoma." (PMID 26035298, 2015). "In particular, in 2005, a chromosomal rearrangement leading to the fusion of the androgen-regulated gene TMPRSS2 and one of the ETS genes, predominantly ERG, was described as being expressed in 40–70% of prostate cancers (PCas) from a radical prostatectomy series." (PMID 25906745, 2015). "For example in mouse models, heterozygosity for PTEN leads to massively increased susceptibility to multiple tumor types, increased cell proliferation in the thyroid and prostate gland, and has been shown to cooperate with other genetic events, such as ERG fusion in murine prostate cancer." (PMID 26672755, 2015). "Additionally, VCaP cells belong to a subtype of prostate cancer that possesses the TMPRSS2:ERG fusion, resulting in the AR driven expression of ERG." (PMID 26571387, 2015). "More recently, it has been shown that the IHC detection of ERG may be a useful marker for vascular tumors, prostate carcinoma and ERG-rearranged Ewing sarcoma." (PMID 25239601, 2014). "In prostate cancer, genomic mutations of DNA repair-associated genes, such as polymerase iota, were positively correlated with TMPRSS2-ERG positive tumors, which associates ERG overexpression with the DNA damage response." (PMID 24504051, 2014). "Although some prostate cancer cell lines, such as VCaP (ERG) and LNCaP (ETV1) are reported to have oncogenic ETS gene rearrangements, the full extent of oncogenic ETS protein expression, including fusion-independent expression, in commonly used prostate cancer cell lines has not been determined." (PMID 24642271, 2014). "Interestingly, polycomb proteins can modulate the hypermethylation of ERG promoters in prostate cancer cells, which also indicates the ERG gene is a hotspot of DNA methylation, especially for tumors with DNA methylation of ERG." (PMID 24739220, 2014). "It is intriguing to note that knockdown of PARP1 poly (ADP-ribose) polymerase 1 (PARP1) in ERG-positive prostate cancer PC3 and DU145 cells may resensitize radioresistant cancer cells." (PMID 24739220, 2014). "EZH2 is a target of ERG, and therefore overexpressed in TMPRSS2:ERG-positive prostate cancers." (PMID 25496077, 2014). "Taken together, these studies support the notion that EMT in high ERG expressers may contribute to drug resistance in prostate carcinoma." (PMID 24504051, 2014). "Interestingly, ADRB2 is also a target gene of two important markers in prostate cancer that are involved in transcriptional regulation; v-ets avian erythroblastosis virus E26 oncogene homolog (ERG) and Enhancer of zeste homolog 2 (EZH2)." (PMID 25629002, 2014). "Ets overexpression may follow chromosome rearrangements, from copy gains of ETV1 in melanoma, to fusion of ERG or ETV1 to the TMPRSS2 promoter, resulting in androgen-inducible expression in prostate cancer, associated with aggressive disease." (PMID 24450640, 2014).
prostate carcinoma (continued). "Our observation of conserved NKX3.1 binding elements in the TMPRSS2 promoter prompted us to examine the hypothesis that NKX3.1 is a repressor of ERG in the TMPRSS2-ERG fusion genomic context in prostate cancer." (PMID 24418414, 2014). "Due to the severe downregulation of DNA repair gene expression in ERG overexpressing cells and in prostate cancer studies, we examined ERG overexpressing cells for the presence of DSBs by performing a neutral comet assay, with and without Ara-C or PKC412 treatments." (PMID 24504051, 2014). "As a result, TDRD1 becomes transcriptionally activated in TMPRSS2:ERG-positive prostate cancer." (PMID 23555854, 2013). "We propose that this epigenetic consequence of the TMPRSS2:ERG fusion represents a novel mechanism which may explain part of the transcriptional modulation induced by ERG in human prostate cancer." (PMID 23555854, 2013). "Interestingly, an increased NF-κB activity was detected particularly in ERG fusion-positive prostate cancer patients and cancer cell lines." (PMID 23915189, 2013). "As NPY is highest expressed in ERG+ prostate cancers it would be interesting to investigate whether ERG+ differ from ERG− prostate cancer bone metastases." (PMID 23390522, 2013). "Functional analyses do not fully explain the selective pressure causing ERG rearrangement during the development of prostate cancer." (PMID 23390522, 2013). "We then investigated whether proteins encoded by the differentially regulated genes are found in different quantities in ERG+ and ERG− prostate cancer tissues." (PMID 23390522, 2013). "Indeed, the TMPRSS2:ERG fusion RNA is shown to be detectable in the urine of men with prostate cancer." (PMID 24133629, 2013). "We propose the model that moderate AR gain in a TMPRSS2:ERG fusion-positive primary prostate cancer might synergistically enhance the expression of ERG, which gives growth advantage to those cells with moderate AR gain." (PMID 24098661, 2013). "Finally, our data suggest that TDRD1 overexpression in ERG-rearranged prostate cancer has a potential of being exploited as a target for prostate cancer immunotherapy." (PMID 23555854, 2013). "Of note, the average level of TDRD1 promoter methylation was inversely correlated with TDRD1 mRNA levels across all 93 samples (ρ = -0.57), suggesting that loss of promoter methylation substantially contributes to TDRD1 overexpression in TMPRSS2:ERG fusion-positive prostate cancer." (PMID 23555854, 2013). "We confirmed NPY overexpression in ERG+ prostate cancer cell lines using qPCR and immunoblotting." (PMID 23390522, 2013). "The present data showed that the loss of p27 expression was correlated with ERG fusion-negative tumors, but did not identify a significant effect of p27 expression on prostate cancer phenotype or patient prognosis." (PMID 24179503, 2013). "Chromosomal rearrangements involving ERG are found in acute myeloid leukemia, acute lymphoblastic leukemia, Ewing’s sarcoma and more than half of all prostate cancers, but the normal physiological function of Erg is unknown." (PMID 23329308, 2013). "To test if TDRD1 may interact with PIWI proteins in TMPRSS2:ERG-positive prostate cancer and thus contribute to the piRNA pathway activity, we measured the mRNA expression of human PIWIL genes in prostate cancer cell lines." (PMID 23555854, 2013). "Given the prevalence of ERG fusions, TDRD1 overexpression is a common alteration in human prostate cancer which may be exploited for diagnostic or therapeutic procedures." (PMID 23555854, 2013). "To gain a better understanding of the mechanisms through which BET inhibitors regulate cell growth and death in prostate cancer cell lines, we analyzed basal expression of BET proteins and several oncogenes that are known drivers in prostate cancer, including ERG, MYC, and AR." (PMID 24293458, 2013). "ERG rearrangement is an early event in the genesis of prostate cancer." (PMID 23390522, 2013).
prostate carcinoma (continued). "NDRG1 gene is also an ETS-family fusion partner in ERG-expressing prostate cancer but unlike TMPRSS2-ERG and SCL45A3-ERG fusions, prevalent in prostate cancers, the NDRG1-ERG fusion is thought to encode for a chimeric protein." (PMID 24386364, 2013). "To determine whether the mitochondrial content is linked to fusion type prostate cancer, we compared MTC02 staining with the ERG-fusion status (obtained by FISH and IHC in 4,818 and 7,500 tumors with MTC02 data) available from our database." (PMID 24261794, 2013). "In ERG negative prostate cancers, strong MTC02 immunostaining was linked to deletions of PTEN, 6q15, 5q21, and early biochemical recurrence (p < 0.0001 each)." (PMID 24261794, 2013). "In the present study, the loss of p27 expression was significantly associated with ERG fusion-negative prostate cancers." (PMID 24179503, 2013). "ERG gene rearrangements are found in about one half of all prostate cancers." (PMID 23390522, 2013). "The TMPRSS2/ERG (T/E) fusion gene is present in the majority of all prostate cancers (PCa)." (PMID 23554889, 2013). "The most common ETS rearrangement is the translocation of the androgen-regulated transmembrane protease serine 2 (TMPRSS2) gene, with the v-ets erythroblastosis virus E26 oncogene homolog gene (ERG) transcription factor accounting for about 85% of all ETS rearrangement-positive prostate cancers." (PMID 23390522, 2013). "Notably, knockdown of the ATM gene expression in HPr-1AR cells can promote androgen-induced TMPRSS2: ERG rearrangement, a prostate-specific chromosome translocation frequently found in prostate cancer cells." (PMID 23272087, 2012). "ERGIC1 silencing specifically regulated the proliferation of ERG oncogene positive prostate cancer cells and inhibited ERG mRNA expression in these cells, indicating that it is a potent drug target in ERG positive subgroup of prostate cancers." (PMID 22761906, 2012). "The fact that androgen treatment alone can induce TMPRSS2: ERG fusion in the prostate cancer, LNCaP, cell line suggests that these cells may contain a detective ATM/ATR DNA damage checkpoint." (PMID 23272087, 2012). "Surprisingly, although ERG1C1 expression was associated with AR and AR driven ERG expression in clinical prostate cancers, no major changes were observed in the expression of ERGIC1 mRNA expression in response to AR silencing." (PMID 22761906, 2012). "Recently the male sex hormone androgen has been demonstrated to promote the recruitment of androgen receptor (AR) and topoisomerase II beta (TOP2B) to genomic breakpoints induced at androgen responsive genes including TMPRSS2: ERG fusion, the most common fusion detected in prostate cancer." (PMID 23272087, 2012). "Thus, in this study, we performed a combinatorial sensitivity screen in ERG positive prostate cancer cells to explore disulfiram mechanism of action in more detail." (PMID 23251544, 2012). "Chinnayian's group has identified androgen regulated prostate-specific serine protease (TMPRSS2) and ERG gene fusions, TMPRSS2-ERG, as the predominant molecular subtype of prostate cancer and demonstrated that TMPRSS2-ERG fusions help in distinguishing between PIN and prostate cancer." (PMID 24213111, 2011). "Hence, it appears that EMT and invasion are general processes which are executed by TMPRSS2/ERG in prostate cancer, and which are achieved by diverse mechanisms." (PMID 21747944, 2011). "Since the discovery of a recurrent gene fusion between the androgen responsive gene TMPRSS2 (transmembrane protease, serine 2) and ERG (v-ets erythroblastosis virus E26 homolog (avian)) on chromosome 21, prostate cancers are molecularly divided into "fusion-positive" and "fusion-negative" cancers." (PMID 22142399, 2011). "In addition, ERG was found in circulating tumor cells from patients with castration-resistant prostate cancer." (PMID 21731703, 2011).
prostate carcinoma (continued). "A significant association between ERG and PIM1 expression in clinical prostate carcinoma specimens was found, suggesting that such a mechanism may be relevant in vivo." (PMID 22140532, 2011). "However, the frequent fusion between TMPRSS2 and the ETS gene ERG showed that gene fusion is a highly relevant event in prostate cancer." (PMID 21298110, 2011). "YK-4-279 can also target a subpopulation of chemoresistant ESFT stem cells and it has been recently described as an effective antiinvasive agent in ETV1 and ERG fusion positive prostate tumors although the mechanism of action of YK-4-279 in prostate cancer cells seems to be different." (PMID 22135504, 2011). "Gene fusions found in prostate cancer often involve the ERG, ETV1, or ETV4 gene." (PMID 21789226, 2011). "The overall data, therefore, indicates that the TMPRSS2-ERG fusion gene and the consequent ERG and CRISP3 overexpression are associated with pathological features related with locally advanced disease in patients with clinically localized prostate cancer." (PMID 21814574, 2011). "We hypothesized that the immunomagnetic enrichment method described herein could be used together with PCA3 and TMPRSS2:ERG assays to specifically detect CTCs in advanced prostate cancer." (PMID 20598135, 2010). "Furthermore, upregulation of ADAMTS1 by ETS transcription factor gene (ERG) has been shown to contribute to an invasive phenotype in prostate cancer." (PMID 20840749, 2010). "A very promising and highly prostate cancer specific marker is the fusion transcript TMPRSS2:ERG." (PMID 24281166, 2010). "Recently, recurrent fusions between the transmembrane protease serine 2 (TMPRSS2) gene and members of the ETS family of transcription factors (mainly the v-ets erythroblastosis virus E26 oncogene homolog (avian), ERG, and the ets variant 1, ETV1) were reported in prostate cancer." (PMID 20964841, 2010). "We hypothesize that these alterations may contribute to the increased invasivity conferred to prostate cancer cells by ERG deregulation." (PMID 20860828, 2010). "The homogeneity analysis using this gene signature supports the hypothesis that ERG rearranged cases represent a distinct subclass, although we cannot extend this result for the entire population of ERG rearranged prostate cancers." (PMID 20233430, 2010). "Detection of PCA3 and/or TMPRSS2:ERG mRNA in whole blood could potentially be used as a prognostic indicator of aggressive prostate cancer." (PMID 20598135, 2010). "The T1/E4 variant is the most common of TMPRSS2:ERG gene fusions and is the best studied; it is not yet known if other variants are associated with prostate cancer prognosis to the same extent." (PMID 18781147, 2008). "The TMPRSS2:ERG gene fusion is specific for prostate cancer, and the ability to identify this DNA rearrangement could be used as a screening test for prostate cancer in serum, prostatic fluid, or in urine." (PMID 18781147, 2008). "The clinical significance of the presence of the TMPRSS2:ERG gene fusion product on prostate cancer presentation and progression is not fully understood, but studies to date suggest that this may be a biomarker of risk." (PMID 18781147, 2008). "Because TMPRSS2 is regulated in the prostate by androgens, it was proposed that this gene rearrangement could be a mechanism whereby the ETV1 or ERG oncogenes were overexpressed, leading to prostate cancer." (PMID 18781147, 2008). "Studies have indicated that TMPRSS2:ERG fusion may co-operate with the loss of the tumor suppressor PTEN and the concomitant activation of AKT to promote the progression of prostate cancer from high-grade prostatic intraepithelial neoplasia (PIN) to invasive prostate carcinoma." (PMID 40332527, 2025). "Androgen treatment of ERG-positive and ERG-negative cells, combined with chromatin immunoprecipitation sequencing, linked sarcosine pathway activation to the androgen receptor and ERG genes, which are key mediators in prostate cancer progression." (PMID 40703706, 2025).
prostate carcinoma (continued). "The TMPRSS2:ERG fusion process has also been described as involved in the regulation of long non-coding RNAs (lncRNAs), which are known to play an important role in the regulation of gene expression and to be deregulated in several types of cancer, including prostate cancer." (PMID 40332527, 2025). "Assuming further that ERG positive cancers might in turn be more dependent on de novo adenine biosynthesis, it would be interesting to learn whether targeting druggable enzymes of this pathway might be efficient in ERG positive prostate cancer." (PMID 40554389, 2025). "However, it is tempting to speculate that this effect could result from the known interaction between ERG and PRMT5 that can only occur in TMPRSS2:ERG fusion positive prostate cancers." (PMID 40554389, 2025). "For example, loss of CHD1 and ZNF292 occurs at a later stage in ERG-positive tumors than in ERG fusion–negative tumors, but as these lesions are common to both progression pathways, these genes seem to be key drivers of prostate cancer progression." (PMID 39347576, 2024). "Additionally, ERG alterations may also have an impact on mTOR signaling pathway activation in primary prostate cancer and the development of castration-resistant disease." (PMID 39125671, 2024). "Western blot analysis confirmed robust downregulation of direct targets (SMARCA2, SMARCA4, and PBRM1) and specific prostate cancer lineage proteins (AR, ERG, C-Myc, and PSA) after 5 d of AU-24118 treatment, whether administered alone or in combination with enzalutamide." (PMID 38557192, 2024). "In prostate cancer, reduced PSAP staining was strongly linked to an advanced pT stage, a high classical and quantitative Gleason score, lymph node metastasis, high pre-operative PSA levels, early PSA recurrence (p < 0.0001 each), high androgen receptor expression, and TMPRSS2:ERG fusions." (PMID 37892063, 2023). "Moreover, ERG mRNA and protein were significantly reduced in prostate cancer cells (VCaP)." (PMID 37310937, 2023). "Thus, it seems that metabolic changes favor ERG rearrangement in prostate cancer." (PMID 37373115, 2023). "Microscopically, while some ERG rearranged prostate cancers are enriched with features such as intraluminal blue mucin and prominent nucleoli, the spectrum of morphology is quite variable and inconsistently predictive of the presence of an ERG rearrangement at the genomic level." (PMID 35513774, 2022). "Importantly, inhibition of ERG activity in prostate cancer cells decreases their viability." (PMID 35267426, 2022). "Moreover, ERG fusion status was not prognostic in patients with intermediate risk prostate cancer treated with radiation." (PMID 35267426, 2022). "Moreover, a recent study shows that ERG can activate cGMP expression in prostate cancer cells." (PMID 35526071, 2022). "Interestingly, eNOS expression could be co-targeted by nuclear receptor ERRα and transcription factor ERG in prostate cancer cells and PCSCs." (PMID 35526071, 2022). "Therefore, ERG cannot be used as a potential diagnostic or prognostic indicator for ovarian cancer, unlike prostate cancer." (PMID 34951103, 2022). "Interestingly, knocking out ERG in ERG-overexpressing, Pten-null organoids did not cause prostate cancer organoids to revert to their Pten-null organoid phenotype, but instead led to an almost normal, glandular-like morphology." (PMID 36212399, 2022). "Therefore, the role of ARPC1B and its correlation with ERG gain and PTEN loss can have an association on cell migration and invasion, which may promote the progression of invasive prostate cancer." (PMID 35163398, 2022).